SFRP5 (secreted frizzled related protein 5)
Description:
Soluble frizzled-related proteins (sFRPS) function as modulators of Wnt signaling through direct interaction with Wnts. They have a role in regulating cell growth and differentiation in specific cell types. SFRP5 may be involved in determining the polarity of photoreceptor, and perhaps, other cells in the retina.
Synonyms: SARP3
Tractability: Antibody: UniProt places it where antibodies can reach, with medium confidence; UniProt predicts a signal peptide or a membrane-spanning region; its Gene Ontology location is reachable by antibodies, with medium confidence.
Gene: Protein-coding gene on chromosome 10 (97,766,751 to 97,771,999, reverse strand). Ensembl gene ENSG00000120057.
Subcellular location: Secreted
Gene Ontology:
Molecular function: Wnt-protein binding
Biological process: digestive tract morphogenesis; negative regulation of canonical Wnt signaling pathway; negative regulation of cell population proliferation; negative regulation of non-canonical Wnt signaling pathway; negative regulation of phosphatidylinositol 3-kinase/protein kinase B signal transduction; regulation of transcription by RNA polymerase II; anatomical structure morphogenesis; apoptotic process; canonical Wnt signaling pathway; establishment or maintenance of cell polarity; negative regulation of Wnt signaling pathway; non-canonical Wnt signaling pathway; signal transduction; visual perception
Cellular component: extracellular region
Genetic constraint (gnomAD): Loss-of-function variants: 22 observed, 25.88 expected, observed/expected ratio (o/e) 0.85, 90% interval 0.61 to 1.21. The upper end of that interval is the gene's LOEUF score, 1.21, which puts it in group 5 of 6, group 1 being the genes least tolerant of losing a copy. Missense variants: 392 observed, 419.16 expected, observed/expected ratio (o/e) 0.94, 90% interval 0.86 to 1.02. Synonymous variants: 163 observed, 186.21 expected, observed/expected ratio (o/e) 0.88, 90% interval 0.77 to 1.
Homologues: Orthologues: chimpanzee SFRP5 (99% identical), macaque SFRP5 (97% identical), rabbit SFRP5 (97% identical), pig SFRP5 (97% identical), dog SFRP5 (96% identical), rat Sfrp5 (94% identical), mouse Sfrp5 (93% identical), guinea pig SFRP5 (89% identical), tropical clawed frog sfrp5 (65% identical), zebrafish sfrp5 (61% identical), Drosophila melanogaster fz3 (20% identical). Paralogues in human: SFRP1 (55% identical), SFRP2 (38% identical), FZD7 (25% identical), FZD8 (25% identical), FZD1 (25% identical), FZD2 (25% identical), FZD10 (24% identical), FZD9 (24% identical), FZD5 (23% identical), FZD4 (22% identical), FZD3 (21% identical), FZD6 (21% identical), and 3 more.
Diseases named in the same sentence as SFRP5 in open-access papers:
SFRP5 is named in the same sentence as 112 diseases in open-access papers, as found by Europe PMC text mining. Sharing a sentence is not in itself a finding about the gene and the disease. The quoted sentences say what the papers report.
Obesity (64 papers, 2006 to 2026). Accumulation of substantial excess body fat. "Our finding that Sfrp5 concentration is associated with blood pressure is also in accordance with other studies in children and adults with obesity, where Sfrp5 was negatively associated with SBP and DBP." (PMID 39339733, 2024). "Background/Objective: Secreted frizzled-related protein 5 (Sfrp5) is an anti-inflammatory adipokine that has been implicated in the pathophysiology of obesity and its metabolic complications." (PMID 39339733, 2024). "Although sufficient evidence suggests that there is downregulation of Sfrp5 in obesity and upregulation after weight loss, much research has revealed contradicting findings." (PMID 39339733, 2024). "This discovery suggests that SFRP5 within adipose tissue holds promise as a potential therapeutic target for addressing glucose homeostasis abnormalities linked to obesity." (PMID 37957661, 2023). "In this sense, given that the adipose tissue-liver axis seems to be relevant in the progression of NAFLD, in this study, we evaluated the SFRP5/WNT5A-PPARγ pathway in adipose tissue samples of women with different degrees of NAFLD associated to obesity." (PMID 36077270, 2022). "On the other hand, adipokines with lower levels in obesity, such as adiponectin and SFRP5, act as anti-tumorigenic agents, and the loss of these effects promotes tumor progression." (PMID 34944905, 2021). "SFRP5 is associated with comorbidities such as obesity, DM2, insulin resistance, and atherosclerosis, inhibiting the wingless-type family member 5a signaling (Wnt5a) and the non-canonical Wnt family and regulating the expression of pro-inflammatory cytokines." (PMID 33807959, 2021). "Intensive exploration showed SFRP5 conditionally exerted an anti-inflammatory effect in response to an obesity-associated microenvironment." (PMID 34284806, 2021). "Lower Sfrp5 serum concentrations were associated with a higher likelihood for obesity and obesity comorbidities, such as elevated blood pressure, carotid intima media thickness, dyslipidemia and inflammation." (PMID 34371968, 2021). "Subsequently, many studies have tried to elucidate the mechanisms through which Sfrp5 and Wnt5a are associated with obesity and cardiometabolic risk factors, as well as their potential role in developing new pharmaceutical compounds." (PMID 34371968, 2021). "Obesity predisposes to decreased SFRP5 and increased WNT5A expression, which has been confirmed in human cohorts with atherosclerosis." (PMID 34948320, 2021). "Concretely, the adipokines, such as leptin, adiponectin, resistin, and other adipokines like visfatin, secreted frizzled-related protein 5 (SFRP5), play an indispensable role in the manipulation of obesity-associated BC." (PMID 34350120, 2021). "SFRP5 correlates with susceptibility to obesity and is highly sensitive to the obesogenic environment." (PMID 34284806, 2021). "These demonstrate that decreased expression of SFRP5 is a prognostic marker for the risk of obesity and T2DM." (PMID 31208019, 2019). "SFRP5 has been reported to be implicated in obesity, insulin resistance, dyslipidemia, and metabolic syndromes." (PMID 30704061, 2019). "Understanding the underlying mechanisms of how SFRP5 can modulate adipogenesis and energy homeostasis highlights its critical role in combating significant public health issues in the form of obesity and T2DM." (PMID 29789397, 2018). "SFRP5 is highly expressed in adipose tissue and has been associated with β-cell function, glucose metabolism, obesity and T2DM." (PMID 29785210, 2018). "In our previous study, we reported that 14 adipocyte genes (Ccl7, Emr1, Evi2a, Gusb, H2-DMb2, Lcp1, LOC100041137, Ly9, Ptpre, Rgs1, sc1000528.1_16, Sirpa, Sfrp5, and Acacb) were associated with both advanced age and diet-induced obesity." (PMID 30282902, 2018).
Obesity (continued). "In contrast to the proposed role of SFRP5 as an anti-inflammatory factor in the previous study, it was shown that SFRP5-deficient mice were resistant to diet-induced obesity and had smaller adipocytes in adipose tissue." (PMID 28796178, 2017). "SFRP5 is a Wnt5a antagonist, therefore, SFRP5 expression loss exaggerated the pro-inflammatory effects of Wnt5a, which was shown to be induced by obesity." (PMID 27608847, 2016). "Fat tissues also produce a smaller number of adipocytokines including adiponectin and Sfrp5, which are beneficial in the setting of obesity-linked complications." (PMID 22835063, 2012). "However, limited data exist concerning the association of Sfrp5 with obesity and its comorbidities in children and adolescents." (PMID 39339733, 2024). "Furthermore, obesity and metabolic dysfunction, including diabetes, are the main comorbidities that are associated with HFpEF, whereas SFRP5 has been previously shown to be influenced by obesity and metabolic dysfunction." (PMID 37504530, 2023). "When caused by obesity, SFRP5 attaches to and prevents Wnt5a." (PMID 36404859, 2022). "SFRP5 is expressed in insulin target tissues such as subcutaneous and visceral adipose tissue, liver, skeletal muscle as well as in beta cells and has been associated with glucose metabolism, obesity, and T2D." (PMID 34184187, 2021). "SFRP5, an inhibitor of Wnt signaling, is tightly associated with obesity and weight gain in mice." (PMID 34489867, 2021). "Notably, other adipokine disorders caused by obesity, including resistin, visfatin, and SFRP5, are also proved to be key orchestrators in BC oncogenesis and progression." (PMID 34350120, 2021). "Meanwhile, SFRP5 deficiency resisted to diet induced obesity by stimulating mitochondrial oxidation activity and increasing SFRP1 compensation, which is mediated in part by peroxisome proliferator-activated receptor gamma coactivator 1 alpha and mitochondrial transcription factor A." (PMID 34489867, 2021). "These in vivo and in vitro data confirmed that the protective effect of RAL against adipocyte inflammation is mediated by SFRP5, which may contribute to the amelioration of obesity-associated metabolic dysfunctions." (PMID 31470850, 2019). "Thus, SFRP5-Wnt5a-JNK regulatory axis in adipose tissue serves as a potential target for the regulation of obesity-associated disorders in glucose homeostasis." (PMID 31470850, 2019). "Additionally, in the pancreatic islets of rats placed on a cafeteria diet, SFRP5 levels were found to be significantly reduced which is implicated in β-cell viability during the β-cell mass expansion in obesity via the Wnt signaling pathway." (PMID 29789397, 2018). "Further understanding of the biological functions implicated may pave the way for SFRP5 to serve as a promising novel therapeutic target in the treatment of obesity, T2DM, and other metabolic diseases." (PMID 29789397, 2018). "For instance, serum SFRP5 level is associated with obesity and type 2 diabetes." (PMID 28824700, 2017). "Epigenetic activation of SFRP5 in WAT increased susceptibility to obesity in HFD-fed mice." (PMID 24624222, 2014). "In addition, circulating SFRP5 was associated with obesity and metabolic syndrome in obese children, and its levels were increased after weight loss." (PMID 24733068, 2014). "These associations between gene expression and variable obesity phenotypes may merely indicate that the changes in expression of SFRP5, MEST, and other genes only result as a consequence of adiposity." (PMID 16733553, 2006). "Thus, our observation that downregulated SFRP5 levels were associated with elevated E/E’ may suggest a new molecular pathway underlying the nexus between obesity/metabolic syndrome and diastolic dysfunction/HFpEF." (PMID 37504530, 2023). "Thus, manipulation the balance between Wnt5a and SFRP5 may represent a potential strategy for management of obesity-associated metabolic abnormalities." (PMID 31470850, 2019).
Obesity (continued). "Furthermore, in SFRP5-deficient mice, JNK1 loss reverses the impaired insulin sensitivity and increased adipose inflammation, suggesting that a deficiency of SFRP5 promotes obesity-induced inflammation and metabolic dysfunction via activation of JNK1 in adipose tissue." (PMID 24733068, 2014). "This upregulation of Sfrp5 is consistent with prior research that examined the impact of an intervention program in children and adults with obesity." (PMID 39339733, 2024). "Sfrp5 decreased in subjects with obesity (p < 0.01); however, it increased significantly (p < 0.05) in patients with morbid obesity." (PMID 39339733, 2024). "In the obesity group, Sfrp5 concentrations correlated positively with BMI (r = 0.48 p < 0.05), SBP (r = 0.61, p < 0.05), and uric acid concentrations (r = 0.707, p < 0.05)." (PMID 39339733, 2024). "We conclude that Sfrp5 is related to obesity and, specifically, to morbid obesity in childhood and adolescence." (PMID 39339733, 2024). "This elevation of Sfrp5, which was evident only in the morbid obesity subgroup, is consistent with prior research in children with obesity (defined as exceeding the 90th and 95th percentile)." (PMID 39339733, 2024). "In line with our findings, fat-biopsy specimens of subjects with obesity with macrophage CLSs presented lower Sfrp5 expression in comparison with subjects with obesity who were negative for CLS." (PMID 39339733, 2024). "Conversely, restoration of SFRP5 levels ameliorated obesity-induced glucose intolerance and hepatic steatosis." (PMID 37504530, 2023). "Conversely, the administration of SFRP5 in mouse models of obesity and diabetes yields contrasting outcomes, enhancing metabolic functionality and mitigating inflammation within adipose tissue." (PMID 37957661, 2023). "Researches also shown that Sfrp5 provides a new goal in glucose homeostasis to regulate obesity-connected disorders." (PMID 36404859, 2022). "This study suggested that the increased expression of SFRP5 in VAT seems to be induced by obesity, and by NAFLD pathogenesis in SAT and VAT, with a potential protective role against metabolic imbalance." (PMID 36077270, 2022). "Our results are consistent with previous reports, which suggested that SFRP5 expression is increased in adipose tissue of models with obesity, inducing adipogenesis." (PMID 36077270, 2022). "SFRP5 is a currently identified adipocytokine related to obesity-related insulin resistance and type 2 diabetes and reduced inflammation." (PMID 36404859, 2022). "In conclusion, we reported and elevated SFRP5 mRNA expression in adipose tissue of patients with NAFLD-related to obesity." (PMID 36077270, 2022). "This review summarizes the current evidence on the emerging role of Sfrp5 and Wnt5a in the pathogenesis of obesity, T2D and cardiovascular disease." (PMID 34371968, 2021). "Previous studies have shown that overexpression of Sfrp5, which is down-regulated in obesity and T2D, can ameliorate impaired glucose tolerance in mice." (PMID 34571259, 2021). "Clinical studies have been conducted to delineate the role of Sfrp5 and Wnt5a in obesity, and the regulation of their secretion in an obesogenic environment." (PMID 34371968, 2021). "Third, obesity related complications also occurred in obese patients with low SFRP5 levels and pro-inflammatory infiltration of visceral tissue." (PMID 34489867, 2021). "These contradictions implied that the functions of SFRP5 in the pathogenesis of T2D and obesity still are little known." (PMID 34184187, 2021). "Circulating SFRP5 expression was also lower in patients with impaired glucose tolerance or type 2 diabetes mellitus and inversely correlated with markers for obesity." (PMID 33573682, 2021). "The purpose of this review is to summarize the current knowledge on the emerging role of Sfrp5 and Wnt5a in the pathogenesis of obesity and its comorbidities both in adults and children." (PMID 34371968, 2021).
Obesity (continued). "The Sfrp5/Wnt5a regulatory system is still relatively unexplored, however, current evidence indicates that it plays a pivotal role in obesity, even in childhood and adolescence." (PMID 34371968, 2021). "Second, SFRP5 is significantly elevated in adipocytes during obesity, including db/db, ob/ob and high fat diet-fed mice." (PMID 34489867, 2021). "This review summarizes the current knowledge on the novel regulatory system of anti-inflammatory Sfrp5 and pro-inflammatory Wnt5a, and their relation to obesity and obesity-related complications." (PMID 34371968, 2021). "Wnt5a and Sfrp5 appear to be critical players in the regulation of systemic inflammation in obesity and glucose homeostasis, as well as mediators between adipose tissue and other key metabolic organs, including the liver and the pancreas." (PMID 34371968, 2021). "In the first instance, regarding obesity, we reported higher serum SFRP5 levels in patients with MO than NW subjects." (PMID 34198988, 2021). "Although WNT5A was reported to be able to regulate cell proliferation and adipogenesis via MAPK, data on the relationships between WNT5A and SFRP5 in humans with obesity are limited and inconsistent." (PMID 33192583, 2020). "Recently, multiple clinical studies demonstrated the relationship between anti‐inflammatory SFRP5 and obesity." (PMID 32004418, 2020). "sFRP5 is a newly identified adipokine that exerts anti-inflammatory effects on metabolic dysfunction in obesity." (PMID 32429518, 2020). "Obesity and adipocyte inflammation increase in the ratio of pro-inflammatory Wnt5a to anti-inflammatory SFRP5." (PMID 32982804, 2020). "In 2012, Schulte and collaborators reported a significant increase of both WNT5A and SFRP5 concentrations in patients suffering from obesity compared with lean patients." (PMID 33192583, 2020). "In contrast, low plasma levels of SFRP5 have been detected in Chinese patients suffering from obesity." (PMID 33192583, 2020). "Certainly, SFRP5 seems to play a critical role in obesity, as well as insulin resistance, and diabetes mellitus." (PMID 33192583, 2020). "In this review, we systematically outlined the current understanding on the roles of SFRP5 in the pathogenesis of three inflammatory diseases including obesity, T2DM and coronary heart disease (CHD)." (PMID 32004418, 2020). "Pro‐inflammatory WNT5A and anti‐inflammatory SFRP5 both play pivotal roles in the development of obesity." (PMID 32004418, 2020). "Studies14, 15, 27 suggested that there was a significantly lower circulating Sfrp5 concentration under conditions of obesity than under conditions of normal weight." (PMID 30120048, 2019). "Among the new adipokines, secreted frizzled-related protein 5 (SFRP5) is considered to prevent obesity and insulin resistance." (PMID 30704061, 2019). "Secreted frizzled-related protein-5 (Sfrp5), known as an anti-inflammatory adipokine, is much more abundant in adipose tissue than other tissues, and negatively affects obesity and obesity-related metabolic disorders." (PMID 30842902, 2019). "On the contrary, anti-inflammatory adipokines such as adiponectin, IL-10, and secreted frizzled-related protein 5 (SFRP5) are downregulated in obesity." (PMID 31475003, 2019). "Previous studies showed that circulating SFRP5 was decreased in patients with impaired glucose tolerance or T2DM and was associated with various obesity-related metabolic parameters." (PMID 30704061, 2019). "Additional studies in human subjects confirmed that lower levels of sFRP-5 are correlated with obesity, impaired glucose tolerance, insulin resistance, and T2D." (PMID 30524198, 2018). "SFRP5 serum levels are correlated with markers of obesity (e.g. BMI, waist-hip ratio, percentage of body fat), and T2DM (e.g. insulin resistance and disorders of lipid metabolism)." (PMID 29785210, 2018).